IGF1R (insulin like growth factor 1 receptor)
Diseases named in the same sentence as IGF1R in open-access papers (continued):
Sharing a sentence is not in itself a finding about the gene and the disease.
tumor (continued). "For instance, picropodophyllin (AXL1717) exhibits noticeable anti-tumor activity in multiple tumors through IGF-1R inhibition, leading to tumor regression, and AXL1717 also interferes with microtubule dynamics, which arrests G2/M phase." (PMID 36233084, 2022). "IGFs effectively bind to IGF-1R and activate pathways associated with cell proliferation, and the interaction between IGFs and IGF-1R promotes tumour cell growth and metastasis." (PMID 36482346, 2022). "In terms of patient outcome, higher tumour INSR expression, and IGF1R expression, was associated significantly with shorter overall survival." (PMID 34554347, 2022). "It is evident that IGF-1R and its ligands play roles in the proliferation and survival of tumor cells." (PMID 35017650, 2022). "Our analysis demonstrated that patients with a combined high expression of HGFR and HER2/neu, EGFR, IGF1R, Mucin-1 and Integrin α2β1 show a very aggressive tumor biology with an impaired median survival compared to HGFR high-expressing tumors alone." (PMID 36359213, 2022). "The level of IGF-1R is frequently increased in malignant tumors, which has been well recognized as a key event in promoting cancer cell proliferation, survival and tumor growth." (PMID 35401828, 2022). "Since cadherin gene expression levels are altered with reduced IGF1R, we further analyzed protein levels in tumor tissues to correlate with gene expression." (PMID 36568144, 2022). "Our results demonstrate that IGF1R promotes metastatic tumor initiation and progression in lung TME." (PMID 35688943, 2022). "It has also been reported that miR-223 promoted apoptosis in tumor cells by targeting the IGF1R/Akt/S6 signaling pathway and increased Erlotinib sensitivity." (PMID 35264191, 2022). "As the IGF1R/IGF1 axis is known to prevent tumor cell death, we counted the dead cells in the cell culture." (PMID 35574343, 2022). "IGF-1R has been shown to be of critical importance for tumor development and tumor cell survival in various types of malignancies." (PMID 36499281, 2022). "Collectively, these data illustrate that ZNRF3*IGF1R PROTABs are tumour-selective for CRC compared with the corresponding normal tissue." (PMID 36131013, 2022). "The increase in IGF-1R activity promotes the proliferation, migration and invasion of cancer cells, and is related to tumor metastasis, drug resistance, poor prognosis and shortened survival time in patients with multiple cancers." (PMID 36497233, 2022). "Cells expressing constitutively active IGF-1R also invade through Matrigel in vitro and form undifferentiated carcinomas in vivo, highlighting that IGF-1R-driven EMT correlates with tumor transformation and invasion." (PMID 36556357, 2022). "Let-7b-5p acts as a tumor suppressor in multiple myeloma, and insulin-like growth factor receptor 1 (IGF1R) is negatively regulated by let-7b-5p at the post-transcriptional level." (PMID 34161325, 2021). "Linsitinib is an IGF‐1R and insulin receptor inhibitor currently under investigation for various types of cancer due to its ability to prevent tumor cell proliferation and induce tumor cell apoptosis." (PMID 34339582, 2021). "Some tumor cells were seen to have weak cytoplasmic IGF1R immunostaining (c-IGF1R 1+) in 121 (75.6%) cases and strong immunostaining (c-IGF1R 2+) in 41 (25.6%) cases." (PMID 34638472, 2021). "Intragenic noncoding RNA (IRAIN) is a lncRNA that acts as a putative tumor suppressor affecting IGF1R expression." (PMID 34681797, 2021). "Among the tumours with IGF1R CN gains, several presented with highly recombined genomes involving hundreds of inter‐ and intra‐chromosomal rearrangements." (PMID 33295144, 2021).
tumor (continued). "In our scoring system, the percentage of IGF1R positive tumor cells was quantified in a more concise manner and we only distinguished between immunostaining intensity scores ranging from 0 to 2 in order to avoid a potential error of central tendency." (PMID 34638472, 2021). "Unbalanced IGF/IGF-1R signaling can promote cancer cell proliferation and activate cancer reprogramming in tumor tissues, especially in the liver." (PMID 33669204, 2021). "Animal experiments showed that spontaneous metastasis of cancer cells occurred after a stable period of anti-IGF1R treatment in NSCLC tumor-bearing mice." (PMID 34335947, 2021). "The acquired resistance to BRAF inhibitors is maintained by IGF1R-driven tumour vascular reconstruction." (PMID 34923978, 2021). "IGF1R is a transmembrane glycoprotein that stimulates the growth of tumor cells by autocrine signaling, induces metastasis, and inhibits apoptosis." (PMID 34503279, 2021). "An in-vitro study reported that GSK1838705A, a potent insulin-like growth factor-1 receptor (IGF1R)/IR inhibitor, is capable of decreasing docetaxel-resistant PCa cell viability and migration, as well as in-vivo tumor growth." (PMID 33692752, 2021). "miR-98 acts as a tumor suppressor, which reduces tumor cell growth and metastasis through targeting the insulin-like growth factor 1 receptor (IGF1R) in OSCCs." (PMID 33917482, 2021). "For example, circ-IGF1R expression is significantly upregulated in HCC tissues and the high expression levels of circ-IGF1R is associated with tumor size." (PMID 34055634, 2021). "A positive correlation was found between the MMP‐2 and IGF‐1R expression in OSCC tumours (p < 0.0001)." (PMID 34528373, 2021). "We also performed immunohistochemistry on tumor tissue sections for the receptors, IGF1R, and cMET, and confirmed their expression." (PMID 34539876, 2021). "It has been demonstrated that the sensitivity of the tumor to hypoxia, low pH and blood glucose concentration can be reduced by IGF1R, suggesting the potential roles of IGF1R signaling in the development the hypoxic TME of PDAC." (PMID 34360896, 2021). "Overall, METTL3‐mediated m6A modification contributes to the upregulation of PCAT6 in an IGF2BP2‐dependent manner and the PCAT6/IGF2BP2/IGF1R complex further stabilizes IGF1R mRNA to activate downstream pathways, which promotes BM and tumor growth in PCa." (PMID 34185427, 2021). "Decorin, the prototype member of the small leucine-rich proteoglycans is a key component of tumor stroma and acts as a tumor suppressor in cancer by down-regulating the activity of several tyrosine-kinase receptors, including the IGF1R and IR-A." (PMID 33673232, 2021). "They showed that VEGF is a downstream component of the MUC1/IGF-1R/AKT cascade and its activation plays an important role in tumor angiogenesis associated with MUC1." (PMID 33836774, 2021). "A significant reduction in tumor size was detected in an ACC xenograft model after a single treatment with anti-IGF1 receptor (IGF1-R) immunoliposomes (SSLD-1H7)." (PMID 34829730, 2021). "Next, a D‐form oligopeptide (cskc) with affinity to insulin‐like growth factor 1 receptor (IGF1R), which is highly expressed on tumor cells, was attached to the PPiP (cskc‐PPiP) for facilitating the NPs’ tumor cell internalization." (PMID 33898169, 2021). "Studies also have revealed that IGF1R contributed to tumor growth and gemcitabine resistance in PDAC." (PMID 35002712, 2021). "A phase 2 trial with the anti-IGF1R mAb R1507 indicated that the treatment was safe but with limited anti-tumor activity as it in fact demonstrated only 2% of partial response and 16% of disease stabilization." (PMID 34440844, 2021). "Consistent with this, the protein levels of IRS1 and IGF1R were also decreased in Lv-mir-150 tumor samples from nude mice, as shown by immunohistochemistry analysis." (PMID 33723215, 2021).
tumor (continued). "IGF1R stimulates tumor metastasis and the secretion of invasion factors to the extracellular matrix, which is independent of the main signaling pathways related to IGF1." (PMID 34178997, 2021). "A total of 11 tumour samples revealed amplifications of IGF1R defined by a ratio between the IGF1R and the centromeric probe >2 (9.2%)." (PMID 33295144, 2021). "The rationale for this research stems from the fact that the IGF1R emerged as a promising therapeutic target in oncology and there is an urgent need to identify tumor biomarkers that can predict therapy success." (PMID 34204736, 2021). "The relevance of nuclear IGF1R in terms of tumor aggressiveness can be inferred from the fact that the inhibition of nuclear IGF1R import correlated with reduced proliferative potential." (PMID 33918477, 2021). "Linsitinib (OSI-906), a selective IGF1R tyrosine kinase inhibitor, can suppress tumor growth and invasion." (PMID 34075028, 2021). "In bulk tumor cells, the IGF1R-induced activation of PI3K-Akt signaling results in radio-resistance by inhibiting cell apoptosis and promoting cell survival." (PMID 34178997, 2021). "Other groups have illustrated that the expression of cancer stemness genes (OCT4, NANOG) induced by elevation of IGF-1/IGF-1R, correlates with high tumor recurrence in HCC patients and sorafenib resistance." (PMID 33669204, 2021). "A positive correlation was also found between EMT markers (FN1 and CDH2) and the IGF‐1R expression in OSCC tumours." (PMID 34528373, 2021). "Unfortunately, IGF1R inhibitors have largely proven inefficient in more than 70 clinical trials on various tumour subtypes." (PMID 33295144, 2021). "Linsitinib (OSI-906) as IGF1R inhibitor suppresses tumor growth and invasion by decreasing cell viability and inducing apoptosis." (PMID 34075028, 2021). "Mechanistically, we show that upon isiPI3K treatment, isiPI3K-sensitive tumor cells upregulate the expression of IGF2 to induce cell proliferation via the activation of the IGF1 receptor (IGF1R)." (PMID 34067117, 2021). "IGF-1R overexpression has been correlated with poor prognosis, high tumor grade, and short overall survival." (PMID 34440625, 2021). "In particular, in colorectal cancer, reduced expression of miRNA-497 has been associated with overexpression of IGF1R and IRS1 with consequent activation of PI3K/Akt signaling, thus contributing to tumor progression, growth, and survival." (PMID 34681797, 2021). "In drug resistance cell group with Trop2 knockdown and IGF1R inhibitor, there were more infiltrating cells between tumor cells." (PMID 34335947, 2021). "This feature of the capture mechanism serves to restrict this unique regulation of IGF-1R signaling to select cell types that express all three receptors, typically tumor cells and endothelial cells undergoing pathological angiogenesis." (PMID 34778093, 2021). "MiR-16 overexpression reduced cell proliferation in vitro and tumor growth in mice by targeting directly the IGF1R with subsequent inhibition of the Raf1- Mitogen-Activated Protein Kinase Kinase 1/2 (MEK1/2)-ERK1/2 pathway." (PMID 34484116, 2021). "In summary, this study reveals that m6A‐modified PCAT6 interacts with IGF2BP2 to stabilize IGF1R mRNA, which promotes PCa BM and tumor growth." (PMID 34185427, 2021). "Several of the hub genes (GATA3, IGF1R, and FOXO3) have been reported to be associated with the tumor progression of ESCC in previous studies." (PMID 33747034, 2021). "DDR1 was critical for IGF-IR endocytosis and trafficking into early endosomes, and DDR1 overexpression induced upregulation of both the IGF1 receptor (IGF1R) and the insulin receptor (IR) in normal and tumor cells." (PMID 34206590, 2021). "The addition of IGF-1R inhibitor linisitinb to treatment schedule of these mice led to a sharp and sustained decrease in tumour size." (PMID 34272384, 2021).
tumor (continued). "The present study showed that the tumour‐promoting activity of OSF on human OSCC cells was attributed to the activation of IGF‐1R, invasion, and EMT in human OSCC cells." (PMID 34528373, 2021). "IGF1R has a potential mitogenic role in promoting cell proliferation, regulating malignant transformation of cells, protecting tumor cells from apoptosis and other biological functions." (PMID 34761108, 2021). "Our ‘in-house’ RNAseq data demonstrate that increased PLEKHS1 expression is significantly associated with high-risk NMIBC (in both G3T1 tumours and CIS) and significant reductions in the expression of IGFBP-2, IGFBP-4, and IGF-1R." (PMID 34681810, 2021). "They further demonstrated that miR-503 acted as tumor suppressor in GBM partially by downregulating its target IGF-1R and interfering with PI3K/AKT pathway." (PMID 33762949, 2021). "In the U2OS and MG63 cell lines, circDOCK1 modulated tumor progression by regulating IGF1R through sponging of miR-339-3p." (PMID 34876132, 2021). "A recent report indicates a potential tumor suppressor role for miR-335-5p in MM through the downregulation of IGF1R." (PMID 34359778, 2021). "Accordingly, dual IGF1R/IR inhibitors have been developed and their efficacy has been proved in different tumor types." (PMID 33673232, 2021). "Increasing type-IV collagen-mediated signaling drastically increases metastases in multiple tumor types, especially those with markedly higher IGF1R expression levels." (PMID 34178997, 2021). "Within the PDAC tissues and correlated with higher tumor grades, it has commonly been found that IGF1R is highly expressed and co-expressed with EGFR, this is likely to lead to poor survival." (PMID 34360896, 2021). "A positive correlation was also found between Cadherin‐2 (CDH2, also known as N‐cadherin) and IGF‐1R expression in OSCC tumours (p < 0.01)." (PMID 34528373, 2021). "In order to corroborate these results obtained by DNA sequencing, an independent set of 119 FFPE tumour samples was examined for IGF1R CN alterations using FISH (fluorescent in situ hybridisation)." (PMID 33295144, 2021). "While, in HNCHPV−, expression of RTKs increases following PI3K treatment, in HNCHPV+, tumor cells acquire resistance to isiPI3K by the secretion of IGF2 to activate IGF1R." (PMID 34067117, 2021). "Let-7b-5p is an established tumor suppressor in MM, which acts by targeting and downregulating, the receptor of insulin-like growth factor (IGF1R) and the oncogene MYC." (PMID 34359778, 2021). "Downregulation of Trop2 in the xenograft model with IGF1R inhibitor significantly decreased the proliferation of tumor cells and remodelled TME." (PMID 34335947, 2021). "A positive correlation was found between the fibronectin (FN1) and IGF‐1R expression in OSCC tumours (p < 0.0001)." (PMID 34528373, 2021). "This anti-oncogenic effect of IGF1R inactivation was reported to involve the modulation of the levels and activation of various effectors required for tumor growth and survival including AKT and ERK1/2." (PMID 32962246, 2020). "Both nuclear and cytoplasmic IGF1R/PCNA colocalization signals were observed at varying levels in tumor tissue." (PMID 32701997, 2020). "The transient combination of the IGF-1R inhibitor with continuous osimertinib eradicated the tumor cells and prevented the regrowth in CDX and PDX models of AXL-low-expressing EGFR-mutated NSCLC." (PMID 32929081, 2020). "Meanwhile, 20 CRC patients’ tumor and paired normal tissues were also collected and used to detect the IR-A and IGF1R mRNA expression." (PMID 33173015, 2020). "We evaluated 4497 CRC samples from 1499 patients for the expression of IGF1R in tumor cells by immunohistochemistry." (PMID 32727431, 2020). "These miRNAs targeted the expression of stathmin-1 and insulin-like growth factor-1 receptor in the tumor cells, functionally inhibiting their proliferation level." (PMID 33066331, 2020).
tumor (continued). "Perhaps the most promising study has utilized post‐IGF‐1R inhibition FDG‐PET to measure tumor metabolic activity as a potential biomarker." (PMID 32115849, 2020). "By investigating two independent tumor cohorts of HGSC and OPSCC, respectively, we found that strong IGF1R/PCNA colocalization was significantly associated with better overall survival." (PMID 32701997, 2020). "Upregulation of growth arrest special 5 (GAS5) has turned out to shrink tumor growth by its key downstream mediator insulin-like growth factor 1 receptor (IGF-1R)." (PMID 32122355, 2020). "KL overexpression or treatment with recombinant KL or sKL decreases colony formation, cell proliferation, migration, and tumor invasion while inducing apoptosis and autophagy through inhibition of Wnt/β-catenin and IGF-1R/AKT/ERK signaling." (PMID 33520985, 2020). "Compared to those with minimal IGF1R expression (IGF1RLow), the IGF1Rhigh fraction significantly enriched the tumor cells to form spheres in vitro and to initiate tumors in vivo (two independent cell lines)." (PMID 33173731, 2020). "As a result, both of them showed a higher expression in tumor tissues than normal controls, but IR-A showed a higher expression in tumor tissues than IGF1R (p<0.05)." (PMID 33173015, 2020). "When labelled with 111In for SPECT imaging, IGF-1 showed good selectivity for tumour cells and strong correlation with IGF-1R expression in human breast cancer cells, suggesting potential application in the molecular imaging of other carcinomas." (PMID 33198090, 2020). "Autocrine activation by the tumor is described in preclinical studies, whereby both the IGF1R and one of its ligands are expressed by the tumor or surrounding tumor stroma." (PMID 33260481, 2020). "IGF-1, through the binding of its receptor IGF-1R expressed in tumor cells, activates PI3K/AKT and MAPK pathways, resulting in their enhanced proliferation." (PMID 32120856, 2020). "As the IGF1R and IR were predominantly expressed in lower tumor stages, this therapeutic approach would be limited to early CRCs." (PMID 32727431, 2020). "Insulin-like growth factor 1 receptor (IGF1-R) is a growth factor that is expressed with and related to tumor progression in some histological subtypes of STS." (PMID 31963219, 2020). "The expression of IGF1R in intact tumor tissues was independently validated by the Western blots and in situ immunofluorescence histochemistry." (PMID 33173731, 2020). "Introduction of antisense IGF-1R decreased cell proliferation and tumor growth of ES cells in vivo and in vitro." (PMID 32754598, 2020). "A new‐generation brain‐penetrable, orally available IGF1R inhibitor harnessing tumor OPCs in the brain is also developed." (PMID 33173731, 2020). "Some of them have been reported to play important roles in the development of tumor proliferation, apoptosis, and metastasis, such as IGF1R, MYBL2, POLE, and DDAH1." (PMID 32923489, 2020). "In AXL-low-expressing tumor cells, EGFR and IGF-1R bind constitutively and to each protein associated with their adaptor proteins, including Gab1." (PMID 32929081, 2020). "In UM, the expression of tumor IGF1R has been associated with disease progression, and the in-vitro inhibition of IGF1R results in tumor regression of UM." (PMID 32911759, 2020). "Membranous IGF1R-expression in tumor cells correlated significantly with IR expression in tumor vessels (p < 0.001) but not with IR status in tumor cells (p = 0.07)." (PMID 32727431, 2020). "In several models of triple negative breast cancer (4T1 and 67NR), CR has been shown to have an additive effect to decrease the primary tumor growth when combined with radiation and was noted to inhibit the IGF-1R/Akt pathway." (PMID 32825010, 2020). "Constitutive activation of IGF-1R can induce ligand-independent neoplasm progression and contribute to the activation of identified oncogenes." (PMID 32546241, 2020).